INS (insulin)
Diseases named in the same sentence as INS in open-access papers (continued):
Sharing a sentence is not in itself a finding about the gene and the disease.
Hypoglycemia (continued). "In a small non-randomized study, 89 patients with T2DM and CKD (mean eGFR 34.1 ± 11.5 mL/min/1.73 m2), who were poorly controlled or experienced frequent hypoglycemia on oral ADs or NPH insulin, were prescribed insulin glargine at bedtime." (PMID 32489427, 2020). "The PEPPER system was designed to analyze user data to deliver real-time hypoglycemia alerts, CBR bolus recommendations, predicted low glucose insulin suspension, and carbohydrate consumption recommendations." (PMID 32517068, 2020). "Under these conditions, the system would protect the brain from potentially damaging hypoglycemia by preventing the release of GLP-1 and subsequently insulin." (PMID 32229720, 2020). "Collectively, these data suggest that endogenously-produced ghrelin not only influences insulin sensitivity, but also is permissive for the normal CRR to insulin-induced hypoglycemia." (PMID 33042003, 2020). "In conclusion, we have shown that fully closed-loop insulin delivery in inpatients receiving parenteral or enteral nutrition (or both) is safe and significantly improves glycaemic control without increasing the risk of hypoglycaemia compared with conventional insulin therapy in non-critical care." (PMID 30935872, 2019). "Other meta-analyses have shown reduction in hypoglycemia, depending upon the definition used, and when including studies comparing CSII with MDI regimens utilizing regular human insulin." (PMID 31250124, 2019). "In patients who are already on insulin therapy for CFRD, practitioners should remain mindful of the potential for hypoglycemia with ivacaftor." (PMID 31010313, 2019). "The expression of c-fos was significantly higher in POMC and MC4R neurons in mice after insulin or 2-DG treatment compared to those injected with PBS, indicating that the neurons were activated following hypoglycemia or glucopenia." (PMID 30503832, 2019). "For medications used in the hypoglycemia group, 6 of the 7 patients used DPP-4 inhibitors, and half of these 6 patients also used insulin secretion stimulators [e.g., sulfonylureas (SU) and glinide] in combination with DPP-4 inhibitors." (PMID 30815039, 2019). "In keeping with their hypoglycemia, RT2 B6 mice were also severely hyperinsulinemic, with an average nine-fold increase in serum insulin compared to wildtype B6 mice." (PMID 30796198, 2019). "In contrast to insulin treatment, the combination of YH1 and OHAs avoided the side effects of hypoglycemia and weight gain." (PMID 31415655, 2019). "The application of orexin, insulin, PACAP, CRF, leptin, CART, CCK, and hypoglycemia (2 mM glucose) to the brain resulted in sympathetic nerve excitation." (PMID 30832213, 2019). "Confocal imaging of triple fluorescent labeled material in fasted, insulin-injected CX3CR1+/gfp mice (microglia reporter strain on C57BL/6 background) revealed close apposition of microglia and hypoglycemia-activated, c-FOS positive neurons." (PMID 30996341, 2019). "The commercially available algorithms are all suspension algorithms, i.e. they can only turn on or off basal insulin delivery, and rely only on CGM measurements for the prediction of future hypoglycemia." (PMID 30922295, 2019). "Individuals who take insulin, which includes all people with T1DM and some people with type 2 diabetes, are prone to hypoglycemia." (PMID 31093506, 2019). "Short-acting insulin analogues are superior to regular human insulin in T1DM patients for the following outcomes: total hypoglycemic episodes, nocturnal hypoglycemia, severe hypoglycemia, postprandial glucose, and HbA1c." (PMID 30622653, 2019). "Coadministration of naloxone and insulin is yet to be tested in animal models of HAAF, as the ideal option would be to select a drug that would be effective for use during established hypoglycemia." (PMID 31013147, 2019). "Hypoglycemia occurs in about 30–60% of patients, and BWS-related neonatal hypoglycemia is due to excess insulin." (PMID 32039119, 2019).
Hypoglycemia (continued). "However in insulin-treated patients at risk of hypoglycaemia, these “hypo clue” symptoms, in particular nausea, falls and unsteadiness, may represent episodes of hypoglycaemia not recognised by the patient." (PMID 28918198, 2018). "DEVOTE demonstrated that in a treat-to-target trial design, insulin degludec was non-inferior to insulin glargine in terms of cardiovascular events and superior with regard to hypoglycaemia risk, with lower rates of both severe and nocturnal severe hypoglycaemia at equivalent glycaemic control." (PMID 28913543, 2018). "Plasma insulin concentrations were higher after the OGTT in the gastrectomy group, and 3 of the patients developed hypoglycemia." (PMID 29548882, 2018). "Furthermore, the lack of data about levels of insulin in infants hampers further analyses and evaluations on impacts of different subtypes on the neonate hyperinsulinemia, or the association between hyperinsulinemia and birthweight or neonate hypoglycemia." (PMID 30355279, 2018). "An ultra-long-acting insulin analogue, insulin degludec, in T1DM showed comparable safety and tolerability and less hypoglycemia when compared with insulin glargine." (PMID 29508275, 2018). "However, this titration may have led to a continuous increase in the insulin dose with consequent hypoglycemia because the fasting glucose levels were mostly regulated by the total morning and evening insulin degludec component of IDegAsp and were therefore inadequate." (PMID 30127860, 2018). "Using standard and high-specificity immunoassays and mass spectrometry, we observed elevated GLP-1, peptide YY (PYY), and insulin levels after glucose ingestion in PTG patients, with consequent hypoglycemia in several participants." (PMID 29548882, 2018). "Efforts to avoid hypoglycemia include patient education, SMBG, and improving insulin delivery through proper delivery devices and techniques." (PMID 29508275, 2018). "In patients with good glycemic control, insulin detemir and insulin glargine (with Regular insulin or bolus insulin) lowered FPG with less nocturnal hypoglycemia when compared with once- or twice-daily NPH insulin." (PMID 29508275, 2018). "Additionally, elevated BHB may have offered protection against hypoglycemic events, as starvation-adapted humans with elevated BHB have demonstrated full preservation of central nervous system function despite profound hypoglycemia induced by exogenous insulin." (PMID 29417495, 2018). "We found evidence that long-acting insulin analogues are efficacious compared to NPH, with estimates showing a reduction in nocturnal hypoglycemia episodes (RR 0.66) and general hypoglycemia episodes (RR = 0.95)." (PMID 29649221, 2018). "In addition, our hypothesis is supported since the insulin/glucagon ratio proved to be positive after the treatments, contributing to ameliorate the hyperglycemic state while it also maintains normal glucagon levels, and protects from hypoglycemia." (PMID 30333575, 2018). "Treatment with intensive insulin regimens is part of our routine clinical practice for all hospitalized patients with T2D but an important proportion of these patients could be highly exposed to suffer hypoglycaemia, which would significantly impact in our clinical practice." (PMID 30208631, 2018). "We observed significantly greater and earlier increases in insulin, GLP-1 and glucagon in patients who had hypoglycaemia in response to an MMT (MMT Hypo) relative to those that did not (MMT Non-Hypo)." (PMID 28855269, 2017). "However, in the Leuven pediatric study, although hypoglycemia was more common in children on intensive insulin therapy and patients developing hypoglycemia had a higher risk of death, this association was not significant and it could be explained by duration of PICU stay." (PMID 28926994, 2017).
Hypoglycemia (continued). "TDI, as well as fingerstick count, shows similar relationships to severe hypoglycemia, that is, from a reference of 41.8U of TDI for an ideal meter, high error rates as well as positive bias will result in higher daily insulin use." (PMID 28569076, 2017). "Thereby, maximum concentrations of insulin and C-peptide were comparable between the RYGB group and more insulin-resistant women with pre-gestational obesity (obese group), resulting in hypoglycaemia in 90% of mothers who had previously undergone RYGB." (PMID 28918470, 2017). "Interestingly, the cut-off values for the fasting glucose levels for predicting nocturnal asymptomatic hypoglycemia were lower in this study than in the previous study, which may be due to more sustained action of the insulin degludec compared to other insulin formulas." (PMID 28683068, 2017). "Insulin should be administered together with glucose in a ratio of 4–6 g glucose for every 1 unit of insulin, with frequent blood glucose monitoring, in order to maintain a high-normal glucose value, since patients with non-diabetic ketoacidosis had high risk for hypoglycemia." (PMID 29258472, 2017). "Based upon the surface under cumulative ranking curve, incretin mimetics were the most effective treatment in reducing the rates of hypoglycemia in T2DM patients fasting during Ramadan, followed by insulin glargine, meglitinides, and finally SU." (PMID 26765440, 2016). "At the relatively high level of insulin used, the STAT mice were less sensitive to hypoglycemia than were the controls, due to their relative insulin insensitivity (resistance)." (PMID 27124954, 2016). "Therefore, DPP-4 inhibitors increase the concentrations of GLP-1 and GIP, which act in pancreatic β-cells by releasing insulin, and in pancreatic α-cells, inhibiting the secretion of glucagon in a glucose-dependent manner, thus controlling blood glucose with no risk of hypoglycemia." (PMID 27471550, 2016). "Thus, higher activity of the AMPK-ACC pathway could block the insulin signaling, via increase IDE expression, corroborating our hypothesis that increase in the degradation of insulin, by the active skeletal muscle, would protect against hypoglycemia during physical activities." (PMID 27467214, 2016). "Increased glucose uptake, lower insulin and glucagon secretion, decreased lipolysis and liver gluconeogenesis are some effects of the massive secretion of IGF2 that lead to hypoglycemia." (PMID 27134683, 2016). "Along the same lines, it has been demonstrated that total annual cost-savings with insulin analogs is 1590 USD per patient, of which 788 USD is hypoglycemia-related cost-savings and 600 USD is due to other DM-related cost-savings." (PMID 27278922, 2016). "The results achieved in this study showed that initiating insulin therapy with BIAsp 30 resulted in lower rates of hypoglycemia, and higher QALYs compared to NPH/Reg insulin." (PMID 27278922, 2016). "In comparison, the per-person annual cost of hypoglycemia in 65–79 year old individuals using sulfonyurea drugs was U.S.$709 and CAN$750, and for insulin was U.S.$1,522, and CAN $2,206." (PMID 27648831, 2016). "Compared to DPP4i users, meglitinides (aHR 1.3, 95 % CI 1.20–1.43) and insulin users (aHR 3.73, 95 % CI 3.35, 4.14) had significantly higher risks for composite CVD, as well as those for stroke, MI, HF, and hypoglycemia." (PMID 26932742, 2016). "In period 2 the proportion of patients with overall hypoglycemia was 17.1 % during treatment with insulin glargine and 16.4 % during treatment with NPH insulin (OR = 1.06; 95 % CI, 0.58 – 1.92)." (PMID 26055391, 2015). "While therapies such as Continuous Subcutaneous Insulin Infusion (CSII) have shown robust improvements in glycemic control, reduced severe hypoglycemia and general QoL, only very few patients in Zambia can afford such therapies." (PMID 25928592, 2015). "MET + SU + insulin, MET + SU + TZD and MET + SU + DPP-4-i increased the odds of hypoglycaemia when compared to MET + SU." (PMID 26664803, 2015).
Hypoglycemia (continued). "In ill patient with DM and other comorbid conditions, Sliding Scale Insulin (SSI) is recommended to maintain tight gycaemic control and avoid gycaemic events (i.e. hypoglycaemia and hyperglycaemia)." (PMID 25977899, 2015). "Studies have shown that insulin pump and CGM (sensor augmented therapy) result in better glucose control, less hypoglycemia, and reduce glucose excursion." (PMID 28702234, 2015). "A total of 21 patients (6.4 %) experienced nocturnal hypoglycemia events during insulin glargine treatment and 24 patients (7.4 %) during NPH insulin treatment." (PMID 26055391, 2015). "Dipeptidyl peptidase 4 (DPP-4) inhibitors increase insulin secretion and suppress glucagon secretion in a glucose-dependent manner through enhancement of the effect of endogenous incretin, thereby improving postprandial glycemic excursion without increasing the risk of hypoglycemia." (PMID 25314300, 2014). "Blocking GLP-1r corrected hypoglycemia in a group of subjects with GB-related postprandial neuroglycopenic hypoglycemia, and the contribution of GLP-1 to postprandial insulin secretion was larger in affected individuals compared to asymptomatic RYGB subjects." (PMID 24951252, 2014). "Hypoglycaemia and weight gain are common side effects of treatment for T2DM and the major barrier to achieving optimal glycaemic control, especially with insulin therapy." (PMID 24607023, 2014). "The dynamic action of insulin and HISS can be determined using the insulin tolerance test; however, the ensuing hypoglycemia limits its use." (PMID 26237598, 2014). "It is due to the structural and biochemical homology between IGF-2 and insulin that an unregulated and elevated level of IGF-2 stimulates glucose metabolism pathways thus leading to hypoglycemia." (PMID 24934576, 2014). "These unexpected changes of hypoglycemia and reduced insulin secretion by anti-CD3 treatment suggest that anti-CD3 therapy lowers blood glucose first, which leads to the reduction of insulin secretion as a consequence." (PMID 24741590, 2014). "In addition to blood pressure control, it is necessary to carefully monitor blood glucose level, because hypoglycemia may develop after tumour removal, due to rebound hyperinsulinism, as the inhibitory effect of norepinephrine on insulin secretion is eliminated." (PMID 24688789, 2014). "A well-established method for inducing hypoglycemia and HPA axis activation is the insulin tolerance test (ITT)." (PMID 24770625, 2014). "In an earlier study in insulin-naïve T2DM patients, age <65 years was an independent predictor of reduced incidence of hypoglycemia (OR 0.76; 95% CI 0.59-0.96)." (PMID 24528773, 2014). "Finally, tight blood glucose control with insulin may lead to episodes of deleterious hypoglycemia." (PMID 26266919, 2014). "Due to the structural and biochemical homology between IGF-2 and insulin, elevated levels of IGF-2 can result in hypoglycemia." (PMID 24934576, 2014). "However recent studies have found that intensive treatment with insulin does not decrease mortality and may even be associated with a higher mortality and hypoglycemia." (PMID 24628829, 2014). "In the face of hypoglycaemia, infants with CHI have inappropriately elevated serum insulin, low ketone bodies, low fatty acids and show a glycaemic response to glucagon." (PMID 24616771, 2013). "When initiating treatment with premixed analogue insulin BID, it is recommended that patients measure BG just before breakfast and dinner as well as when there are symptoms consistent with hypoglycemia." (PMID 24011173, 2013). "A major advantage over conventional insulin is the fact that the insulinotropic actions of GLP-1 are dependent upon ambient glucose concentration, mitigating the risks of hypoglycemia." (PMID 23777457, 2013).
Hypoglycemia (continued). "However, in the normal C57BL/6J mice, although Diapin treatment decreased the casual blood glucose levels at 30 and 60 min, the postprandial glucose levels remained in normal range, indicating that Diapin does not cause hypoglycemia even under non-insulin resistance conditions." (PMID 24386218, 2013). "In fact, pioglitazone, DPP-4 inhibitors, GLP-1 agonists and acarbose, unlike insulin, could all have some beneficial effect on cardiovascular risk; furthermore, they do not induce hypoglycemia, which is negative cardiovascular mortality and they require no regular blood glucose self-monitoring." (PMID 24348585, 2013). "Among the observational trials which reported hypoglycaemia rates 16,41,43,45,46,62, between 2 and 12% of patients experienced hypoglycaemia while on the combination of exenatide BID and insulin." (PMID 23061470, 2013). "Insulin impairs IGFBP-1 gene expression, and, as a consequence, high levels of IGFBP-1 are present in diabetes mellitus and low levels are noted during hypoglycaemia in patients with congenital hyperinsulinism." (PMID 24228030, 2013). "When an insulin therapy is initiated in a patient with T2DM, an attempt should be made at minimizing the adverse effects of treatment and most notably hypoglycemia and weight gain." (PMID 24348585, 2013). "The GLP-1 secretion is preserved during hypoglycemia and GLP-1 enhances glucose-induced insulin secretion from the pancreatic β-cells via the G-protein coupled GLP-1R leading to an intracellular cAMP increase." (PMID 23543638, 2013). "Clinical trials and other observational studies have reported similar 3,4,6 or lower overall rates of hypoglycaemia 5,8 or a lower rate of nocturnal events 3,4 in GLP-1 receptor agonist versus insulin treatment." (PMID 23330649, 2013). "The frequent use of insulin and secretagogues proved to be effective in rapid achieving of the target HbA1c in ACCORD but with more adverse events such as hypoglycemia." (PMID 21977022, 2012). "Substitution of long-acting (e.g., glargine or determir) insulin for intermediate- acting insulin (e.g., NPH or premix 70/30) reduces frequency of nocturnal and daytime hypoglycemia." (PMID 23497433, 2012). "After the injection of insulin, rats became hypoglycemic, but with the SSTR2 antagonist, hypoglycemia was avoided." (PMID 22969729, 2012). "The reasons for delaying insulin initiation are varied, but may include patient and physician perceptions that insulin therapy regimens are too complex, concerns about self-administering injections, or fears regarding side effects such as hypoglycaemia and weight gain." (PMID 21481127, 2011). "Despite higher insulin doses, those taking MET alone had less hypoglycaemia than those taking SU or MET + SU." (PMID 21481127, 2011). "However, when sitagliptin is added to ongoing therapy with a sulfonylurea or insulin, there is an increase in the incidence of hypoglycemia compared with the addition of placebo as might be expected when an agent that provides additional glycemic efficacy is used in combination with these agents." (PMID 20412573, 2010). "Basal insulin (NPH or analogue) or a sulfonylurea is the preferred next step in treatment intensification, although other agents may be more appropriate for an individual patient (e.g. a patient susceptible to or concerned about hypoglycaemia, with contraindications to or intolerance of metformin)." (PMID 20089006, 2010). "However, results from some individual studies included in this pooled analysis (in which sitagliptin was added to either a sulfonylurea with or without metformin or to insulin with or without metformin) demonstrated an increased risk for hypoglycemia with sitagliptin relative to placebo." (PMID 20412573, 2010). "One reason for this dilemma might be that intravenous (IV) insulin protocols have been designed to lower BG in order to achieve a 'normal' or 'optimal' BG target range, without consideration for their tendency to cause hypoglycemia." (PMID 19822000, 2009).